MSANTD4 (Myb/SANT DNA binding domain containing 4 with coiled-coils)
Synonyms: KIAA1826
Tractability: PROTAC: UniProt records ubiquitination sites on it; ubiquitination databases record sites on it.
Gene: Protein-coding gene on chromosome 11 (105,995,623 to 106,022,410, reverse strand). Ensembl gene ENSG00000170903.
Subcellular location (Human Protein Atlas): Nucleoplasm; Cytosol
Gene Ontology:
Molecular function: protein binding
Cellular component: nucleus
Genetic constraint (gnomAD): Loss-of-function variants: 15 observed, 35.89 expected, observed/expected ratio (o/e) 0.42, 90% interval 0.28 to 0.64. The upper end of that interval is the gene's LOEUF score, 0.64, which puts it in group 2 of 6, group 1 being the genes least tolerant of losing a copy. Missense variants: 358 observed, 417.22 expected, observed/expected ratio (o/e) 0.86, 90% interval 0.79 to 0.94. Synonymous variants: 137 observed, 153.67 expected, observed/expected ratio (o/e) 0.89, 90% interval 0.77 to 1.03.
Homologues: Orthologues: macaque MSANTD4 (100% identical), rabbit MSANTD4 (98% identical), pig MSANTD4 (97% identical), chimpanzee MSANTD4 (96% identical), guinea pig MSANTD4 (96% identical), dog MSANTD4 (95% identical), rat Msantd4 (95% identical), mouse Msantd4 (94% identical), tropical clawed frog msantd4 (71% identical), zebrafish msantd4 (53% identical).
Diseases named in the same sentence as MSANTD4 in open-access papers:
MSANTD4 is named in the same sentence as 4 diseases in open-access papers, as found by Europe PMC text mining. Sharing a sentence is not in itself a finding about the gene and the disease. The quoted sentences say what the papers report.
Huntington disease (1 paper, 2023). Huntington disease (HD) is a rare neurodegenerative disorder of the central nervous system characterized by unwanted choreatic movements, behavioral and psychiatric disturbances and dementia. "While MSANTD4 has been linked to Huntington’s disease, and ZBED4 has been linked to schizophrenia and Phelan-McDermid syndrome in recent studies, little is known about these proteins' underlying mechanisms." (PMID 37047316, 2023).
MSANTD4 also shares sentences with these, for which no sentence is quoted: Alzheimer disease (1 paper); Phelan-McDermid syndrome (1); schizophrenia (1).